KCND3 (potassium voltage-gated channel subfamily D member 3)
Description:
Pore-forming (alpha) subunit of voltage-gated A-type potassium channels that mediates transmembrane potassium transport in excitable membranes, in brain and heart. In cardiomyocytes, may generate the transient outward potassium current I(To) (By similarity). In neurons, may conduct the transient subthreshold somatodendritic A-type potassium current (ISA) (By similarity). Kinetics properties are characterized by fast activation at subthreshold membrane potentials, rapid inactivation, and quick recovery from inactivation. Channel properties are modulated by interactions with regulatory subunits. Interaction with the regulatory subunits KCNIP1 or KCNIP2 modulates the channel gating kinetics namely channel activation and inactivation kinetics and rate of recovery from inactivation. Likewise, interaction with DPP6 modulates the channel gating kinetics namely channel activation and inactivation kinetics.
Synonyms: Kv4.3; KSHIVB; BRGDA9; KCND3L; KCND3S; SCA19; SCA22
Tractability: Small molecule: an approved drug acts on it; a high-quality ligand is known; it belongs to a druggable protein family. Antibody: UniProt places it where antibodies can reach, with high confidence; its Gene Ontology location is reachable by antibodies, with high confidence; UniProt predicts a signal peptide or a membrane-spanning region. PROTAC: its protein half-life has been measured; a small molecule that binds it is known.
Target class: Potassium channels; Ion channel; Voltage-gated ion channel; Voltage-gated potassium channel
Gene: Protein-coding gene on chromosome 1 (111,770,662 to 111,989,668, reverse strand). Ensembl gene ENSG00000171385.
Subcellular location: Cell membrane; Cell membrane, sarcolemma; Cell projection, dendrite
Pathways (Reactome):
Muscle contraction: Phase 1 - inactivation of fast Na+ channels
Neuronal System: Voltage gated Potassium channels
Gene Ontology:
Molecular function: A-type (transient outward) potassium channel activity; protein binding; voltage-gated potassium channel activity involved in ventricular cardiac muscle cell action potential repolarization; voltage-gated potassium channel activity involved in cardiac muscle cell action potential repolarization; monoatomic ion channel activity; voltage-gated potassium channel activity
Biological process: membrane repolarization; potassium ion export across plasma membrane; potassium ion transmembrane transport; potassium ion transport; protein tetramerization; regulation of heart rate by cardiac conduction; ventricular cardiac muscle cell membrane repolarization; action potential; chemical synaptic transmission; membrane repolarization during cardiac muscle cell action potential; muscle contraction; regulation of heart contraction; membrane repolarization during ventricular cardiac muscle cell action potential; monoatomic ion transport; protein homooligomerization; transmembrane transport
Cellular component: Kv4.3-KChIP1 channel complex; plasma membrane; voltage-gated potassium channel complex; dendritic spine; neuronal cell body; postsynaptic membrane; dendrite; GABA-ergic synapse; membrane; postsynaptic specialization membrane; sarcolemma
Genetic constraint (gnomAD): Loss-of-function variants: 9 observed, 51.77 expected, observed/expected ratio (o/e) 0.17, 90% interval 0.1 to 0.3. The upper end of that interval is the gene's LOEUF score, 0.3, which puts it in group 1 of 6, group 1 being the genes least tolerant of losing a copy. Missense variants: 526 observed, 935.33 expected, observed/expected ratio (o/e) 0.56, 90% interval 0.52 to 0.6. Synonymous variants: 349 observed, 384.14 expected, observed/expected ratio (o/e) 0.91, 90% interval 0.83 to 0.99.
Gene-disease validity (ClinGen):
ClinGen rates the evidence that KCND3 causes each of these diseases.
Brugada syndrome 1 (autosomal dominant): Disputed.
Homologues: Orthologues: chimpanzee KCND3 (100% identical), macaque KCND3 (100% identical), rat Kcnd3 (99% identical), guinea pig KCND3 (99% identical), mouse Kcnd3 (99% identical), pig KCND3 (99% identical), rabbit KCND3 (99% identical), dog KCND3 (99% identical), tropical clawed frog kcnd3 (92% identical), zebrafish kcnd3 (75% identical), Drosophila melanogaster Shal (58% identical). Paralogues in human: KCND2 (74% identical), KCND1 (65% identical), KCNB2 (29% identical), KCNA4 (26% identical), KCNC3 (26% identical), KCNA2 (26% identical), KCNA3 (26% identical), KCNA5 (26% identical), KCNA1 (26% identical), KCNC2 (26% identical), KCNC4 (26% identical), and 19 more.
Diseases named in the same sentence as KCND3 in open-access papers:
KCND3 is named in the same sentence as 120 diseases in open-access papers, as found by Europe PMC text mining. Sharing a sentence is not in itself a finding about the gene and the disease. The quoted sentences say what the papers report.
Brugada syndrome (26 papers, 2011 to 2025). A genetically heterogeneous condition characterized by complete or incomplete right bundle branch block accompanied by ST elevation in leads V1-V3. "The last variant associated with the AIP index was KCND3 rs6703437, which codes for a potassium channel responsible for smooth muscle contraction and is associated with Brugada syndrome and cardiac conduction." (PMID 37372394, 2023). "Functional gain and loss of the potassium ion channel coded by KCND3 can cause cardiac channelopathies (Brugada syndrome, early-onset atrial fibrillation, early repolarization syndrome) and spinocerebellar ataxia subsequently." (PMID 36883079, 2023). "Several KCND3 mutations of autosomal dominant inheritance were reported associated with Brugada syndrome (BrS) and spinocerebellar ataxia (SCA)." (PMID 36883079, 2023). "KCND3, one of the genes expressed both in the heart and brain, is reported to have an association with Brugada syndrome, early-onset atrial fibrillation, early repolarization syndrome, and sudden unexplained death syndrome." (PMID 36883079, 2023). "In summary, the KCND3 gene is associated with different cardiac channelopathies, mainly Brugada syndrome, early-onset atrial fibrillation, early repolarization syndrome, and sudden unexplained death syndrome." (PMID 36883079, 2023). "Previously, another gain-of-function KCND3 variant, p.L450F, was originally linked to the Brugada syndrome; however, this variant was later identified in a patient with cerebellar gait ataxia but no significant heart problems." (PMID 34361012, 2021). "In contrast, gain-of-function mutations in the KCND3 gene are linked to cardiac arrhythmia, the Brugada syndrome." (PMID 34361012, 2021). "Some recent studies have shown that the mutation of KCND3 is closely related to cerebellar ataxia, Brugada syndrome and long QT syndrome." (PMID 34029013, 2021). "Recently, loss-of function mutations in KCND3 (potassium voltage-gated channel, Shal-related subfamily, member 3) have been identified causing SCA19/22, whereas gain-of function mutations in KCND3 were implicated in Brugada syndrome and atrial fibrillation." (PMID 26189493, 2015). "It has been documented that an increase of Ito amplitude by gain-of-function mutations in the KCND3-encoded Kv4.3 channels is the molecular pathogenesis for the lethal arrhythmia in patients with Brugada syndrome." (PMID 23526953, 2013). "The increase of Ito amplitude by gain-of-function mutations in KCND3-encoded Kv4.3 channels is the molecular pathogenesis for the lethal arrhythmia in patients with Brugada syndrome." (PMID 23272117, 2012). "Interestingly, the gain-of-function mutations associated with Brugada syndrome have been identified in KCND3 and KCND2 encoding Kv4.2, which constitutes a Kv channel tetramer, along with Kv4.3 in vivo." (PMID 40334257, 2025). "Mutations of KCND3 have been illustrated to be culpable for the channelopathies including early repolarization syndrome (ERS), Brugada syndrome (BrS), atrial fibrillation (AF) of early-onset, sudden unexplained cardiac death syndrome with negative autopsy." (PMID 36883079, 2023). "Gain-of-function mutations in KCND3, the gene encoding the Ito carrying KV4.3 channel, have been associated with Brugada syndrome (BrS)." (PMID 29593552, 2018). "Previously, variants and mutations in KCND3 were found to be associated with sudden unexpected death syndrome (SUDS) and later with Brugada syndrome-9 (BRGDA9)." (PMID 29527639, 2018). "Multiple mutations in KCND3 have been reported to be associated with the pathogenesis of dominantly inherited spinocerebellar ataxia (SCA) 19/22, Brugada syndrome (BrS) and sudden unexplained death syndrome." (PMID 29383177, 2017). "Several mutations in KCND3 were identified in dominantly inherited spinocerebellar ataxia (SCA) 19/22, early-onset of persistent lone atrial fibrillation, Brugada syndrome (BrS) and a case of sudden unexplained death." (PMID 29383177, 2017).
Brugada syndrome (continued). "Expression of KCND3 is altered in inherited and acquired cardiac pathologies such as Brugada syndrome or congestive heart failure." (PMID 22039467, 2011). "Most of the studies of KCND3 focus on cerebellar ataxia, Brugada syndrome and long QT syndrome." (PMID 34029013, 2021).
Ataxia (25 papers, 2015 to 2025). Ataxia refers to impaired coordination of voluntary muscle movement. "Third, transcriptomic analysis revealed that at an early stage before the manifestation of the ataxia phenotype, many down‐regulated DEGs related to the Kcnd3 F227del mutation can be identified." (PMID 39562497, 2025). "First, the Kcnd3 F227del mutation causes an early onset of an ataxia phenotype that affects motor coordination and balance in both sexes." (PMID 39562497, 2025). "Pathogenic loss-of-function variants in the KCND3 gene cause the AD spinocerebellar ataxia (SCA) 19/22, while gain-of-function variants cause cardiological disorders." (PMID 36835207, 2023). "A novel KCND3 c.1054A>G (p.T352A) variant was reported in a patient with cerebellar ataxia from a Korean family." (PMID 36883079, 2023). "In this study, Sanger sequencing was used to screen 115 probands of cerebellar ataxia families in 67 patients with sporadic cerebellar ataxia and 200 healthy people to identify KCND3 mutations." (PMID 35813061, 2022). "To investigate the patients with KCND3 mutation, we performed a screening targeting KCND3 in a cohort of undiagnosed cerebellar ataxia patients, including the families of 115 probands and 67 sporadic cerebellar ataxia patients." (PMID 35813061, 2022). "KCND3-related ataxia is further known to be associated with a wide range of disease onset (from very early ages to later stages of life), as well as distinctly different clinical courses (including episodic, non-progressive, and slowly progressive)." (PMID 34361012, 2021). "In this study, we report the identification of a rare KCND3 c.1256G>A (p.R419H) variant in a patient with cerebellar ataxia, parkinsonism, cognitive impairment, and brain iron accumulation." (PMID 34361012, 2021). "Here, we aim to ascertain the potential pathogenic role of KCND3 variant in iron accumulation-related cerebellar ataxia." (PMID 34361012, 2021). "So far, only one ataxia patient harboring the mutation L450P in KCND3 has been diagnosed with Brugada syndrome A.." (PMID 29527639, 2018). "Penetrance of KCND3 mutations associated with ataxia is very high as shown in the Swedish family; reduced penetrance has been described only once for KCND3 mutations (M373I)." (PMID 29527639, 2018). "The spectrum of KCND3 mutations constitutes a unique cardiocerebral syndrome; KCND3 is the only known ataxia gene associated with cardiac arrhythmia so far." (PMID 29527639, 2018). "The Thr377Met (T377M) mutation in KCND3 has been described only once in a Japanese patient affected by pure cerebellar ataxia." (PMID 29527639, 2018). "The analysis of trio WES data revealed both compound heterozygous variants in PMPCA and a de novo variant in KCND3 in an individual with DD, ataxia, epilepsy, Hirschsprung disease, and abnormal mitochondrial function (Complex I and III deficiency)." (PMID 28327206, 2017). "We identified a de novo KCND3 mutation causing the most marked change in Kv4.3’s channel properties reported so far, which correlated with a severe and unique spinocerebellar ataxia (SCA) type 19/22 disease phenotype." (PMID 26189493, 2015). "KCND3 was identified as a locus associated with ataxia in 2013." (PMID 40140957, 2025). "Nonetheless, some of the cardiopathogenic gain-of-function KCND3 mutations may also be related to neurological disorders such as ataxia, cognitive dysfunction, and epilepsy." (PMID 34361012, 2021). "It remains unclear, however, whether ataxia-related KCND3 variants may be associated with brain iron accumulation." (PMID 34361012, 2021). "Twelve variants in KCND3 have been associated with spinocerebellar ataxia (SCA19/22)." (PMID 32709127, 2020). "Mutations in KCND3 are an uncommon cause of cerebellar ataxia." (PMID 26189493, 2015). "Moreover, it has been shown that mutations in KCND3 cause spinocerebellar ataxia." (PMID 30679814, 2019).
Ataxia (continued). "This is in contrast to the obvious ataxia phenotype, namely motor coordination and balance defects that have developed at this age in the Kcnd3 F227del mice." (PMID 39562497, 2025). "Gain-of-function of the Ito channel caused by mutated KCND3 leads to BrS, AF, and ERS, and on the other hand, loss-of-function mutation of the channel causes spinocerebellar ataxia." (PMID 36883079, 2023). "Patients with KCND3-related neurological disorders are characterized by heterogeneous clinical presentations including cerebellar ataxia, cognitive dysfunction, and movement disorders such as parkinsonism." (PMID 34361012, 2021). "Identification of the first de novo mutation in potassium voltage-gated channel, shal-related subfamily, member 3 (KCND3) in a patient with complex early onset cerebellar ataxia in order to expand the genetic and phenotypic spectrum." (PMID 26189493, 2015). "Therefore, we performed a screening targeting KCND3 in a cohort of undiagnosed cerebellar ataxia patients." (PMID 35813061, 2022). "KCND3 gene deficiency, associated to SCA19/22, is a complex neurological syndrome encompassing a still expanding spectrum of neurological features beside ataxia." (PMID 32823520, 2020). "Due to the limited follow-up of these patients, it is uncertain if in a subset of KCND3 patients, EA may anticipate the development of a progressive ataxia as seen in other channelopathies." (PMID 32823520, 2020). "Finally, no ataxia phenotypes were detectable in knockout mice carrying a loss‐of‐function Kcnd3 mutation." (PMID 39562497, 2025). "The degeneration and a minor loss of Purkinje cells, together with the concurrent presence of neuroinflammation, as well as the previous finding on electrophysiological changes, may all contribute to the development of the SCA22 ataxia phenotype in mice carrying the Kcnd3 F227del mutant protein." (PMID 39562497, 2025). "Finally, the ataxia phenotype is not present in heterozygous and homozygous Kcnd3 KO mice carrying a loss‐of‐function null allele of Kcnd3 up to 9 months of age." (PMID 39562497, 2025). "This provides convincing genetic evidence to demonstrate that the ataxia phenotype manifesting in human SCA22 patients and in heterozygous KI/+ mice is not caused by haploinsufficiency, but rather by Kcnd3 F227del being a dominant‐negative mutation." (PMID 39562497, 2025). "At 4 months of age, both the heterozygous and the homozygous Kcnd3 KO mice showed no overt phenotype in terms of growth and reproduction, and neither did they show any observable abnormalities including the ataxia phenotype." (PMID 39562497, 2025). "Furthermore, the Kcnd3 KO (−/−) mice have no overt ataxia phenotype up to 9 months old." (PMID 39562497, 2025).
epilepsy (19 papers, 2015 to 2025). A brain disorder characterized by episodes of abnormally increased neuronal discharge resulting in transient episodes of sensory or motor neurological dysfunction, or psychic dysfunction. "KCND3 V392I mutation induced cardiocerebral channelopathy in two siblings displaying both cerebral ( intellectual disability & epilepsy) and cardiac (paroxysmal AF and ERS) phenotypes." (PMID 36883079, 2023). "ERS associated with epilepsy and AF has been reported in another six-year-old patient who was found to have a missense mutation in the KCND3 gene, making the association between cardiocerebral channelopathy and ERS evident in these individuals." (PMID 36883079, 2023). "PAF associated with ERS and epilepsy was found in a six-year-old girl whose genetic study revealed a missense mutation in the KCND3 gene." (PMID 36883079, 2023). "Mutation in 916 G>A (G306S) KCND3 has been reported in another eight-year-old patient having atrial fibrillation, epilepsy, and developmental delay." (PMID 36883079, 2023). "Since the epileptic phenotype appears to manifest prior to cardiac events in this mutation carrier, identifying KCND3 mutations in patients with epilepsy and providing optimal therapy will help prevent sudden unexpected death in epilepsy." (PMID 33920294, 2021). "More than 80 patients have been reported over time, broadening the clinical spectrum of KCND3 deficiency to include epilepsy, intellectual disability/cognitive impairment, movement disorders, pyramidal signs, and peripheral neuropathy." (PMID 32823520, 2020). "KCND3 mutation caused simultaneous epilepsy, developmental delay, and atrial fibrillation." (PMID 36883079, 2023). "Patients harboring a KCND3 V392I mutation exhibit both cardiac (early repolarization syndrome and paroxysmal atrial fibrillation) and cerebral (epilepsy) phenotypes, which may be associated with a unique mixed electrophysiological property of V392I-Kv4.3." (PMID 33920294, 2021).
Arrhythmia (16 papers, 2011 to 2026). Any cardiac rhythm other than the normal sinus rhythm. "Therefore, our findings expand the spectrum of mutations in KCND3 that cause the pathogenesis of AF and various forms of cardiac arrhythmias." (PMID 29383177, 2017). "KCND3 encodes voltage-gated potassium channel D3 (Kv4.3) and mutations have been associated with spinocerebellar ataxia type 19/22 (SCA19/22) and cardiac arrhythmias." (PMID 37446101, 2023). "The resulting paradigm shift is likely to open new perspectives for genetic screening of cardiac arrhythmia and other channelopathies caused by SCNXA or KCND3 variants." (PMID 32709127, 2020). "The most induced genes were also ABCC9 and KCND3 (27- and 18-fold, P < 1 × 10−20), which code for sulfonylurea receptor 2 and potassium voltage-gated channel subfamily D member 3, important genes in cardiac arrhythmia." (PMID 41481712, 2026). "This scarcity of cases precludes the delineation of clear genotype-phenotype correlations at the moment; however, risk stratification for cardiac arrhythmia is warranted in patients with KCND3 mutations regardless of the mutation type or location within the gene." (PMID 29527639, 2018).